CFTR (CF transmembrane conductance regulator)
Diseases named in the same sentence as CFTR in open-access papers (continued):
Sharing a sentence is not in itself a finding about the gene and the disease.
cystic fibrosis (continued). "The most prevalent CFTR mutation, ∆F508, is found in ∼90% of cystic fibrosis patients, where it impairs CFTR folding, inhibits channel gating, and decreases PM stability." (PMID 36589230, 2022). "Cystic fibrosis is a genetic disease caused by mutations in the cystic fibrosis transmembrane conductance regulator (CFTR), which results in exaggerated airway inflammation, airway edema and impaired host defense." (PMID 36532044, 2022). "CF is a genetic condition affecting the gene encoding the cystic fibrosis transmembrane conductance regulator (CFTR), localized on the epithelial cells in multiple organs, including the pancreas." (PMID 39872972, 2022). "In cystic fibrosis, mutations in the CF transmembrane conductance regulator protein reduce ionic exchange in the lung, resulting in thicker mucus, which impairs mucociliary function, airway inflammation and infection." (PMID 35888988, 2022). "Cystic fibrosis is a multiorgan disease caused by the mutation of the cystic fibrosis conductance regulator (CFTR) gene, which encodes a membrane protein that regulates chloride and fluid transport across multiple epithelia and exocrine organs." (PMID 36076992, 2022). "CF is associated with mutations in the gene coding for the cystic fibrosis transmembrane conductance regulator (CFTR) protein." (PMID 36677301, 2022). "CF is caused by a mutation in the gene responsible for the cystic fibrosis transmembrane conductance regulator (CFTR)." (PMID 35267909, 2022). "Cystic Fibrosis is a life-threatening disease due to various mutations in the CF transmembrane conductance regulator (CFTR) gene." (PMID 35669174, 2022). "In cystic fibrosis, the loss of cystic fibrosis transmembrane conductance regulator (CFTR) mediated Cl− and HCO3− secretion across the epithelium acidifies the airway surface liquid (ASL)." (PMID 36073059, 2022). "Cystic fibrosis is a multiorgan disease caused by genetic impairment of CF transmembrane conductance regulator (CFTR) function." (PMID 36416119, 2022). "Cystic fibrosis is a multi-system disease caused by mutations in a gene that leads to a defective or missing CF transmembrane conductance regulator (CFTR)." (PMID 35564849, 2022). "Although cystic fibrosis is recognized as a monogenic disease, due to variants within the CFTR (Cystic Fibrosis Transmembrane Regulator) gene, an extreme clinical heterogeneity is described among people with CF (pwCF)." (PMID 36430680, 2022). "The pathogenic mechanism of cystic fibrosis includes the functional interaction of the cystic fibrosis transmembrane conductance regulator (CFTR) protein with the epithelial sodium channel (ENaC)." (PMID 35462606, 2022). "CF is caused by mutations in the cystic fibrosis transmembrane conductance regulator (CFTR, also named ABCC7) gene leading to abnormal mucus in the lung, pancreas, gastro-intestinal tract and reproductive tract." (PMID 35265034, 2022). "Mutations in the cystic fibrosis transmembrane conductance regulator (CFTR) gene leads to impaired bicarbonate secretion contributing to CF airway pathology." (PMID 35392868, 2022). "Cystic fibrosis is an autosomal recessive genetic disease, which is caused by CFTR gene mutation leading to CFTR protein misfolding, defective transport, and impaired function." (PMID 35651949, 2022). "Cystic fibrosis is caused by a mutated cystic fibrosis transmembrane conductance regulator (CFTR) gene, leading to a deficient chloride, bicarbonate and fluid transport across the apical surface of the epithelial organs." (PMID 35633718, 2022). "The importance of determining the complete genotype of patients with cystic fibrosis and, especially, identifying complex alleles in patients carrying the F508del mutation to predict the response to treatment and confirm the effectiveness of new combined complex CFTR modulators is emphasized." (PMID 36286063, 2022).
cystic fibrosis (continued). "Cystic fibrosis is an autosomal recessive disease due to the occurrence of mutations in the CF transmembrane conductance regulator (CFTR) gene." (PMID 36294716, 2022). "Cystic fibrosis is a hereditary autosomal recessive disorder caused by a range of mutations in the CF Transmembrane Conductance Regulator (CFTR) gene." (PMID 35944004, 2022). "CF is caused by mutations in the gene encoding the cystic fibrosis transmembrane conductance regulator (CFTR) ion channel, which transports chloride and bicarbonate to maintain osmotic balance across multiple epithelial surfaces." (PMID 36081767, 2022). "Cystic fibrosis is an autosomal recessive disorder attributed to the mutations of a gene that encodes the cystic fibrosis transmembrane conductance regulator (CFTR) protein." (PMID 35819638, 2022). "Cystic Fibrosis results from over 400 different disease-causing mutations in the CF Transmembrane Conductance Regulator (CFTR) gene." (PMID 36467478, 2022). "Cystic fibrosis is a monogenic disease with an estimated incidence of 1 in 2500 newborns, which is caused bygenetic mutations in the CFTR gene." (PMID 35455577, 2022). "Hepatobiliary involvement is a hallmark in cystic fibrosis, as the causative CF Transmembrane Conductance Regulator (CFTR) defect is expressed in the biliary tree." (PMID 36293293, 2022). "Cystic fibrosis is a monogenic, recessive disease caused by mutations in the gene encoding for the cystic fibrosis transmembrane conductance regulator (CFTR) protein." (PMID 36293514, 2022). "Cystic fibrosis is a lethal autosomal-recessive inherited disease caused by mutations in the cystic fibrosis transmembrane conductance regulator (CFTR) gene." (PMID 34977268, 2022). "Alterations in the cystic fibrosis transmembrane conductance regulator (CFTR) gene can cause the autosomal recessive condition cystic fibrosis." (PMID 34426854, 2022). "The development of preclinical in vitro models has provided significant progress to the studies of cystic fibrosis, a frequently fatal monogenic disease caused by mutations in the gene encoding the CF transmembrane conductance regulator (CFTR) protein." (PMID 36013270, 2022). "Cystic fibrosis is an autosomal recessive genetic disease that is caused by mutations in the CF transmembrane conductance regulator (CFTR) protein." (PMID 36359406, 2022). "CF is a genetic disease characterized by loss of function mutations in cystic fibrosis transconductance membrane regulator (CFTR), a cAMP-activated chloride channel expressed in many tissues." (PMID 38213468, 2022). "Cystic fibrosis is an autosomal recessive disorder caused by congenital mutations in the cystic fibrosis transmembrane conductance regulator (CFTR) gene." (PMID 35888988, 2022). "The genetic disease CF is caused by a variety of mutations in the gene coding for the cystic fibrosis transmembrane conductance regulator (CFTR) protein responsible for ion transport across the cellular membrane." (PMID 36362282, 2022). "Defective hydration of airway surface mucosa is associated with recurrent lung infection in cystic fibrosis, a disease caused by CF transmembrane conductance regulator (CFTR) gene mutations." (PMID 35563895, 2022). "Cystic fibrosis is an autosomal recessive disease caused by two mutations in the gene encoding the cystic fibrosis transmembrane conductance regulator (CFTR) protein which is found in the membranes of most epithelial cells in the human body." (PMID 35210925, 2022). "Recent advances in small molecule therapies have greatly improved the outlook for those with cystic fibrosis caused by certain mutations in the CF transmembrane conductance regulator (CFTR)." (PMID 35446787, 2022). "Cystic fibrosis is the most common inherited disease in the Caucasian population and it is caused by pathogenetic variants in a gene that encodes the cystic fibrosis transmembrane conductance regulator (CFTR) protein and it is expressed in many epithelial and blood cells." (PMID 36360353, 2022).
cystic fibrosis (continued). "Pathophysiology of CF is caused by mutations in the Cystic Fibrosis Transmembrane Conductance Regulator (CFTR) gene, whose protein product is localized primarily in the apical membrane of secretory epithelial cells." (PMID 35156780, 2022). "In addition, cystic fibrosis, a heritable disease, is caused by a defect in the ATP-activated chloride channel, cystic fibrosis transmembrane conductance regulator (CFTR) which is involved in water flow control during the production of sweat, digestive fluids, and mucus." (PMID 35837274, 2022). "Cystic fibrosis, the most common genetically inherited disease in Caucasian populations, is a multi-systemic life-threatening autosomal recessive disorder caused by mutations in the cystic fibrosis transmembrane conductance regulator (CFTR) gene on the long arm of chromosome 7." (PMID 36293274, 2022). "Cystic fibrosis is a multisystem disease caused by mutation of the gene encoding for the cystic fibrosis transmembrane conductance regulator (CFTR) protein." (PMID 35456789, 2022). "Cystic fibrosis is the most common monogenic disorder, caused by mutations in the CF transmembrane conductance regulator (CFTR) gene." (PMID 35740997, 2022). "Cystic fibrosis is an autosomal recessive disorder caused by a mutation in CF transmembrane conductance regulator (CFTR) gene." (PMID 35757256, 2022). "Cystic fibrosis is a life-limiting autosomal recessive disorder due to variants in the CF Transmembrane Conductance Regulator (CFTR) gene." (PMID 35927765, 2022). "The disease-causing gene involved in CF is the cystic fibrosis transmembrane conductance regulator (CFTR), which encodes a gating channel responsible for the transport of chloride ions (Cl−) across the cell membrane." (PMID 35062937, 2022). "Cystic fibrosis is caused by mutations in the CFTR gene that decrease the number and/or function of CFTR ion channels on the cell membrane, leading to abnormal chloride and bicarbonate secretion." (PMID 35456026, 2022). "Cystic fibrosis is caused by variants of the cystic fibrosis transmembrane conductance regulator (CFTR) gene and leads to multi-organ disease particularly affecting the respiratory system." (PMID 35906215, 2022). "Additionally, the site equivalent to the most widespread cystic fibrosis linked mutant, (CFTR delF506) Ycf1 F713, is located in NBD1 directly adjacent to the phosphorylation sites of the R-domain and is coordinated by cation-pi interactions with two conserved arginine side chains, R765 and R1150." (PMID 35277487, 2022). "This is highlighted by the fact that Na+ absorption is abnormally elevated in defective airways in cystic fibrosis, a common genetic disease caused by CFTR mutations." (PMID 36111343, 2022). "The fundamental reason for CF is mutations in cystic fibrosis transmembrane conductance regulator (CFTR) genes coding the CFTR protein, which is located at the apical membrane of epithelial cells." (PMID 35844763, 2022). "Cystic fibrosis is caused by mutations in the cAMP-regulated, phosphorylation gated anion channel cystic fibrosis transmembrane conductance regulator (CFTR)." (PMID 35327663, 2022). "Cystic Fibrosis is a multisystem disorder resulting from pathogenic mutations in the CF transmembrane conductance regulator (CFTR) gene." (PMID 35875368, 2022). "Cystic Fibrosis is an inherited recessive disease that results from mutations in the Cystic fibrosis transmembrane conductance regulator (CFTR) gene." (PMID 35330693, 2022). "Cystic fibrosis is an autosomal recessive disorder caused by a mutation in the gene encoding for cystic fibrosis transmembrane conductance regulator (CFTR)." (PMID 33968061, 2021). "Data from Italian Cystic Fibrosis Registry show that only 21.1% of CF patients are homozygous for F508del CFTR mutation." (PMID 34356748, 2021). "Cystic fibrosis is a chronic, hereditary, multi-organ disease caused by absence or dysfunction of the cystic fibrosis transmembrane conductance regulator (CFTR) protein." (PMID 34073663, 2021).
cystic fibrosis (continued). "Most of the ~2100 CFTR variants so far reported are very rare and still uncharacterized regarding their cystic fibrosis disease liability." (PMID 35008443, 2021). "Cystic fibrosis is an autosomal recessive genetic disease, which is characterized by causing variants in the cystic fibrosis transmembrane conductance regulator (CFTR) gene, that is located in chromosome 7." (PMID 34874053, 2021). "Cystic fibrosis is a life‐limiting autosomal recessive genetic disease caused by variants in the CFTR gene, most commonly by the [F508del] variant." (PMID 34086412, 2021). "However, this combination of symptoms may also occur in cystic fibrosis, a genetic disorder due to mutations in the cystic fibrosis transmembrane conductance regulator (CFTR) gene." (PMID 33853553, 2021). "Cystic fibrosis is an autosomal recessive disease that causes alterations in the cystic fibrosis transmembrane conductance regulator (CFTR) chloride ion channel, leading to thick mucus blocking the airway, causing infections and scarring of the lung." (PMID 33467161, 2021). "Cystic fibrosis is a complex multi-organ disease caused by mutations in the cystic fibrosis transmembrane conductance regulator gene (CFTR gene)." (PMID 33808590, 2021). "Cystic fibrosis is a life limiting disease caused by mutations in the cystic fibrosis transmembrane conductance regulator (CFTR) gene." (PMID 33671516, 2021). "CF is caused by mutations of the cystic fibrosis transmembrane conductance regulator (CFTR) gene that spans about 250 kb of genomic DNA; it is located at chromosomal region 7q31.2 and contains 27 exons." (PMID 38624701, 2021). "Cystic fibrosis is a genetic disease caused by mutations in the cystic fibrosis transmembrane conductance regulator gene (CFTR)." (PMID 34394004, 2021). "CF is caused by mutations in the cystic fibrosis transmembrane conductance regulator (CFTR) gene, which lead to impaired ion transport in a variety of different secretory epithelial cell types from the airways to the intestine." (PMID 33804918, 2021). "Cystic fibrosis is the most common lethal genetic disorder, caused by mutations in the gene encoding for Cystic Fibrosis Transmembrane Conductance Regulator (CFTR), a channel responsible for chloride (Cl−) and bicarbonate (HCO3−) transport in epithelial cells." (PMID 34065744, 2021). "Cystic fibrosis is an autosomal recessive disease caused by the mutation of the cystic fibrosis transmembrane conductance regulator (CFTR) gene, located in the chromosome 7." (PMID 33859572, 2021). "Cystic fibrosis is an autosomal recessive genetic disease characterized by mutations in the cystic fibrosis transmembrane conductance regulator (CFTR) gene." (PMID 34356748, 2021). "Cystic fibrosis is a chronic lung disorder caused by genetic mutations leading to functional defects in the cystic fibrosis transmembrane conductance regulator (CFTR), a chloride channel that regulates the flow of chloride ions in epithelial cells." (PMID 34887860, 2021). "Cystic fibrosis is an inherited recessive disease caused by multiple mutations in a single cystic fibrosis transmembrane conductance regulator (CFTR) gene." (PMID 34683710, 2021). "In contrast, CF is caused by mutations in the cystic fibrosis transmembrane conductance regulator (CFTR) gene, which is translated into proteins function as chloride channels in surface airway epithelial cells and the cells of the submucosal glands." (PMID 33937932, 2021). "Autosomal-recessive cystic fibrosis is due to mutation of the cystic fibrosis transmembrane conductance regulator (CFTR), a cellular membrane protein that acts on chloride ion channels in epithelial cells." (PMID 33562240, 2021). "Cystic Fibrosis is caused by mutations on the CF transmembrane conductance regulator (CFTR) gene and is associated with chronic infection and inflammation." (PMID 34440900, 2021).
cystic fibrosis (continued). "Cystic fibrosis, is caused by mutations within the gene encoding the cystic fibrosis transmembrane conductance regulator (CFTR), which results in defective autophagy, causing the accumulation of CFTR containing aggregates." (PMID 34930105, 2021). "CF is caused due to the mutations in the cystic fibrosis transmembrane conductance regulator (CFTR) gene." (PMID 35071057, 2021). "Cystic fibrosis is an autosomal-recessive disease caused by mutations in the CF transmembrane conductance regulator (CFTR) gene." (PMID 32661789, 2021). "CF is caused by mutations in the cystic fibrosis transmembrane conductance regulator (CFTR) gene which encodes a protein of the same name." (PMID 34063507, 2021). "The CF gene encodes for a protein the cystic fibrosis transmembrance conductance regulator (CFTR) which is a protein chloride channel that belongs to the family of adenosine triphosphate (ATP)-binding cassette (ABC) transporters." (PMID 34717671, 2021). "CF is a channelopathy caused by mutations in the cystic fibrosis transmembrane conductance regulator (CFTR) gene, impairing Cl- channel function." (PMID 34944156, 2021). "Cystic fibrosis is a potentially fatal multi-organ disease caused by mutation of the cystic fibrosis transmembrane conductance regulator (CFTR) gene." (PMID 35011616, 2021). "Cystic fibrosis, one of the most frequent genetic diseases, is caused by mutations that impair the expression and function of CFTR chloride channel." (PMID 33652850, 2021). "CF is a well-known genetic disorder caused by a mutated cystic fibrosis transmembrane conductance regulator (CFTR) protein." (PMID 34161396, 2021). "CF is an autosomal recessive disease that is caused by mutations in the cystic fibrosis transmembrane conductance regulator (CFTR) gene." (PMID 33450950, 2021). "CF is caused by mutations of the cystic fibrosis transmembrane conductance regulator (CFTR) channel." (PMID 35011607, 2021). "Cystic fibrosis is a life-threatening autosomal recessive disease caused by more than 2100 mutations in the CF transmembrane conductance regulator (CFTR) gene, generating variability in disease severity among individuals with CF sharing the same CFTR genotype." (PMID 34782688, 2021). "Cystic fibrosis pulmonary disease is the culmination of a series of events consequential to mutations in the CF transmembrane conductance regulator (CFTR)." (PMID 33802742, 2021). "CF is a hereditary disease (MIM #219700) caused by mutations in the cystic fibrosis transmembrane conductance regulator (CFTR) gene (MIM *602421)." (PMID 33572515, 2021). "Mutations in CFTR lead to cystic fibrosis commonly affecting the lungs, liver, intestine, and pancreas." (PMID 34768335, 2021). "HCO3− secretion is impaired in CF due to mutations in the gene encoding the cystic fibrosis transmembrane conductance regulator (CFTR) protein." (PMID 34200909, 2021). "The cystic fibrosis transmembrane conductance regulator (CFTR) is an anion channel whose dysfunction causes cystic fibrosis." (PMID 34382377, 2021). "CF is a recessive disease resulting from mutations in a single gene that encodes a protein called Cystic Fibrosis Transmembrane Conductance Regulator (CFTR)." (PMID 34831067, 2021). "CFTR, the cystic fibrosis gene-encoded epithelial anion channel, has a prominent role in driving chloride, bicarbonate and fluid secretion in the ductal cells of the exocrine pancreas." (PMID 35011616, 2021). "In cystic fibrosis, a mutation in both alleles of the CFTR gene leads to the production of a CFTR protein that is insufficient in structure, length, quantity or stability, depending on the exact mutation." (PMID 34442455, 2021). "Cystic fibrosis is caused by loss of function of the cystic fibrosis transmembrane conductance regulator (CFTR), an apically located chloride and bicarbonate ion channel in airway epithelial cells." (PMID 34514718, 2021).